NGB (neuroglobin)
Diseases named in the same sentence as NGB in open-access papers (continued):
Sharing a sentence is not in itself a finding about the gene and the disease.
glioma (3 papers, 2019 to 2021). A benign or malignant brain and spinal cord tumor that arises from glial cells (astrocytes, oligodendrocytes, ependymal cells). "In particular, Hu and colleagues provided different evidence, which supports the direct role of NGB as an antiapoptotic protein in glioma tumors against oxidative stress." (PMID 31354909, 2019). "Consistently, the analysis of both NGB mRNA and protein levels strongly sustained an upregulation of NGB levels in glioma tissue with respect to the normal counterpart." (PMID 31354909, 2019). "The correlation between NGB expression and the worse clinic-pathological feature, type/grade of glioma, poor prognosis, and shorter survival overall led to proposing NGB as a prognostic marker for glioma patients." (PMID 31354909, 2019). "Mechanically, it has been proposed that NGB could favor glioma progression and a malignant phenotype by preserving cancer cells from apoptosis against oxidative pressure through the direct regulation of the antiapoptotic PI3K/AKT pathway." (PMID 31354909, 2019). "Spot E also contains genes related to hemoglobin function such as HBA1, neuroglobin (NGB), and SRBP1, which upregulate in glioma tissues under hypoxic conditions." (PMID 34206856, 2021). "On the one side, they proved that NGB overexpression protects U87 glioma cells against cell death induced by 4-hydroxy-2-nonenal (4-HNE), an end-product of the reaction between ROS and polyunsaturated fatty acids, which reflects a high oxidative stress inside cells." (PMID 31354909, 2019).
lung carcinoma (3 papers, 2016 to 2023). "In lung cancer, the upregulation of NGB mRNA was associated with the increase of the hypoxia-inducing factor HIF1, revealing that NGB may be regulated in a hypoxic-dependent manner as a defense mechanism to enable cancer cells to adapt to the tumor microenvironment." (PMID 37005662, 2023). "On the other hand, the hypoxia-dependent up-regulation of NGB mRNA has been assessed in lung cancer cells even if no information is available on the protein level." (PMID 27149623, 2016). "In addition, Oleksiewicz and colleagues confirmed the overexpression of NGB in non-small cell lung cancer (NSCLC) specimens with respect to their matched normal tissue and in a panel of cell lines derived by lung cancer suggesting a NGB procancerous function even in extra-nervous tumors." (PMID 31354909, 2019).
subarachnoid hemorrhage (3 papers, 2019 to 2022). A serious neurological disorder characterized by intracranial hemorrhage into the subarachnoid space. "For example in adults, neuroglobin gene haplotype has a strong influence on outcome after TBI, bcl-2 gene single nucleotide polymorphisms also influence outcome after TBI, and apoE genotype predicts outcome following subarachnoid hemorrhage." (PMID 31275228, 2019). "Indeed, rabbits treated with neuroglobin coupled with TAT transduction domain (TAT-Ngb) had improved neuronal outcome in terms of a significant reduction in apoptotic mechanisms in a model of subarachnoid hemorrhage." (PMID 34440676, 2021).
breast ductal carcinoma (2 papers, 2020 to 2021). "Here, we evaluated the levels and localization of NGB in ERα+ breast ductal carcinoma tissue of different grades derived from pre-and post-menopausal patients." (PMID 34440755, 2021). "The ductal carcinoma of G3-grade tissue showed a higher NGB immunoreactivity compared to G2 tissues in both whole lysate and subcellular fraction." (PMID 34440755, 2021). "The association here reported between ERα phosphorylation, AKT activation, and NGB accumulation strongly sustain that a similar pathway is also active in ERα+ ductal carcinoma tissues." (PMID 34440755, 2021). "This evidence prompted us to evaluate if the NGB accumulation reported in cancer cells is a conserved compensatory mechanism important for ERα+ ductal carcinoma progression." (PMID 34440755, 2021).
Breast Tumors (2 papers, 2020 to 2021). "Our data indicate that NGB is greatly accumulated in all breast tumor samples analyzed with respect to their normal counterparts, where the protein levels are barely detected." (PMID 34440755, 2021). "To complicate further the scenario about the functional role of NGB in breast tumors, we demonstrated that a great immunoreactivity of NGB is localized near the border of the duct close to the lumen." (PMID 34440755, 2021). "Furthermore, the effects of extracellular NGB on ERα+/ERα− cancer cells and non-transformed epithelial mammary cells strongly sustain that the released globin can function in whole breast tumor environment, which commonly show a strong spatial and temporal heterogeneity in terms of cell composition." (PMID 32872414, 2020).
Cognitive impairment (2 papers, 2020 to 2022). Abnormal cognition is characterized by deficits in thinking, reasoning, or remembering. "Thus, people with lower levels of NGB in the brain may be at higher risk of cognitive impairment, especially in the elderly as a consequence of the higher levels of toxic Aβ species generated." (PMID 33343276, 2020). "We investigated the value of serum neuroglobin in predicting cognitive impairment after ICH." (PMID 35463129, 2022). "The goal of our research was to see if neuroglobin may be used as a biomarker for cognitive impairment following ICH." (PMID 35463129, 2022). "Then we calculated the difference in plasma NGB levels between V5 and V1 and compared the degree of change between donors who stayed cognitively stable at V5 (Stables; n = 14) and donors who showed a mild cognitive impairment (MCI) at V5 (converters; n = 7)." (PMID 33343276, 2020).
diabetic retinopathy (2 papers, 2021 to 2024). "Both NGB and OTX2 have biological links to eye health, therefore we focused on investigating the association between DNA methylation at these two genes and diabetic retinopathy status in T2D cases." (PMID 38574408, 2024). "Three of the 20 T2D-DMPs reached genome wide significance at FDR 5% and were located in genes with possible links to diabetic complications such as blood pressure, cardiovascular disease and diabetic retinopathy (RGL3, NGB and OTX2)." (PMID 38574408, 2024).
hepatoma (2 papers, 2014 to 2019). "A similar E2-induced antiapoptotic function has also been reported in the hepatoma cell HepG2 in contrast with the antiproliferative and tumor-suppressor function of the overexpressed NGB reported by other authors in these cells." (PMID 31354909, 2019). "Here, we report the existence of an E2-induced NGB upregulation pathway for cell survival in both hepatoma (HepG2) and breast adenocarcinoma (MCF-7) cells, where the E2-pro-oncogenic signals prevail." (PMID 25299774, 2014). "In hepatoma cells, evidence suggests a role of NGB as on oxygen/ROS sensor, where it could act by coupling oxygen/ROS signals with a signal cascade, in particular, suppressing the Raf/MEK/ERK pathway via a regulatory machinery, which may involve other NGB-interacting proteins." (PMID 31354909, 2019).
Huntington disease (2 papers, 2021 to 2022). Huntington disease (HD) is a rare neurodegenerative disorder of the central nervous system characterized by unwanted choreatic movements, behavioral and psychiatric disturbances and dementia. "Italian scholars have found that the causative gene of Huntington's disease can damage the 17β-estradiol/neuroglobin signaling pathway, thereby affecting neuronal survival, suggesting that neuroglobin is involved in the pathogenic mechanism of Huntington's disease." (PMID 35463129, 2022).
ischemic stroke (2 papers, 2012 to 2021). A stroke disorder caused by obstruction of blood flow to the brain, due to thrombotic (local blood clot formation) or embolic (due to a blood clot or other material traveling from another site) event. "Very soon after neuroglobin was first discovered Greenberg and others, in a series of studies, conclusively showed that neuroglobin is protective in transfected animal models of ischaemic stroke." (PMID 24710547, 2012). "More recently, studies have proceeded to transgenic animal models constitutively over-expressing neuroglobin and these have supported the previous findings that over expression of neuroglobin can typically reduce brain neuron cell death by approximately 30% in ischemic stroke." (PMID 24710547, 2012). "In contrast, neuroglobin mRNA levels increase in the cerebral cortex of female rats, but not in the male cortex, after ischemic stroke." (PMID 34440676, 2021).
arteriovenous malformation (1 paper, 2022). "Another study showed that neuroglobin expression was significantly increased in the surrounding neurons of arteriovenous malformation and ICH patients and in the perihematoma area near cerebral hemorrhage, which may be involved in neuroprotection after brain injury." (PMID 35463129, 2022).
astrocytoma (1 paper, 2019). "NGB expressions have been found higher in the mouse and the human astrocytoma cell line and in human astrocytoma tissues with respect to the normal astrocytes, sustaining a possible role of NGB in the adaptation of astrocytoma to the hypoxic and oxidative stress conditions." (PMID 31354909, 2019).
Ataxia (1 paper, 2024). Ataxia refers to impaired coordination of voluntary muscle movement. "To better understand the involvement of NGB in neuroprotection, we targeted the cerebellum from these mice since they develop ataxia as they age." (PMID 38796706, 2024). "Thus, without sharing functional properties with apoptosis-inducing factor, neuroglobin was efficient in reducing ataxia in Harlequin mice." (PMID 38796706, 2024).
cardiac hypertrophy (1 paper, 2022). "Genes associate with cardiac hypertrophy included JMJD1C, ANXA7, TRIM8, NGB, and AKAP13." (PMID 36071494, 2022).
cerebral infarction (1 paper, 2022). An ischemic condition of the brain, producing a persistent focal neurological deficit in the area of distribution of the cerebral arteries. "Another study showed that neuroglobin could be detected in multiple regions after cerebral infarction, and its expression was significantly increased in the ischemic penumbra." (PMID 35463129, 2022).
cognitive decline (1 paper, 2022). "Serum neuroglobin may serve as a potential biomarker to predict cognitive decline after ICH." (PMID 35463129, 2022).
colorectal cancer (1 paper, 2023). A primary or metastatic malignant neoplasm that affects the colon or rectum. "But, the function of NGB in colorectal cancer is still unclear, especially the role of epigenetics in regulating NGB." (PMID 37005662, 2023).
glioblastoma (1 paper, 2010). The most malignant astrocytic tumor (WHO grade IV). "In agreement with this hypothesis, a recent particular study has shown that neuroglobin is up-regulated in hypoxic microregions of glioblastoma tumour xenografts." (PMID 20640154, 2010).
hematoma (1 paper, 2022). A hematoma is a collection of blood from a vascular structure into an extravascular space. "In Model 2, after further adjustment for NHISS scores and Hematoma volumes, serum neuroglobin concentration was also an independent risk predictor for PSCI after ICH (β = 0.311, p = 0.038)." (PMID 35463129, 2022). "Correlation analysis showed that age, gender, LDL, FBG, SBP, DBP, NHISS and hematoma volume were negatively correlated with MoCA (p < 0.05), while education, HDL and serum neuroglobin were positively correlated with MoCA (p < 0.05)." (PMID 35463129, 2022). "Age, gender, LDL, FBG, SBP, DBP, NHISS, and Hematoma volume were found to be adversely connected with MoCA (p < 0.05), while education, HDL, and serum neuroglobin were found to be positively correlated with MoCA (p < 0.05)." (PMID 35463129, 2022).
hemorrhagic stroke (1 paper, 2022). A stroke caused by a bleed on the brain. "The role of neuroglobin in hemorrhagic stroke has also received increasing attention." (PMID 35463129, 2022).
intracerebral hemorrhage (1 paper, 2022). A cerebrovascular disorder characterized by bleeding into one or both cerebral hemispheres including the basal ganglia and the cerebral cortex. "The aim of our current study was to determine whether neuroglobin could serve as a biomarker for cognitive prognosis in patients with intracerebral hemorrhage (ICH)." (PMID 35463129, 2022).
Neurofibrillary tangles (1 paper, 2016). Pathological protein aggregates formed by hyperphosphorylation of a microtubule-associated protein known as tau, causing it to aggregate in an insoluble form. "In addition, ERα interaction with neurofibrillary tangle and NGB-Aβ complexes suggest that proteins aggregates with ERα and NGB may inhibit their functions, therefore de-regulation impairs neuroprotective effect in AD." (PMID 27313512, 2016).
optic atrophy (1 paper, 2022). A disorder characterized by loss of optic nerve fibers. "Furthermore, Harlequin mutant mice that display retinal ganglion cell loss and optic atrophy, due to a respiratory chain complex I defect, have a 2‐fold reduced neuroglobin expression." (PMID 35656861, 2022). "Supporting this conservation, we found that tripentadecanoin induces the expression of neuroglobin, protects or rescues cells against toxic amyloids and prevents NMU‐induced photoreceptor damage in mice and optic atrophy in Rhesus monkeys." (PMID 35656861, 2022).
Parkinson disease (1 paper, 2022). A progressive degenerative disorder of the central nervous system characterized by loss of dopamine producing neurons in the substantia nigra and the presence of Lewy bodies in the substantia nigra and locus coeruleus. "In addition, the expression of neuroglobin present in the substantia nigra and striatum was upregulated in a mouse model of Parkinson's disease, suggesting that neuroglobin may be involved in the mechanism of its pathogenesis." (PMID 35463129, 2022).
proteinopathies (1 paper, 2022). "Together, we propose that tripentadecanoin affects p‐bodies to induce neuroglobin expression and offers a potential treatment for proteinopathies and retinal neurodegeneration." (PMID 35656861, 2022).
retinal diseases (1 paper, 2021). "On the other side, just few human studies about the connection between NGB levels and retinal disease have been yet performed." (PMID 34831423, 2021). "The discovering of the intracellular monomeric globin neuroglobin (NGB), found at high concentration in the retina, has opened new possibilities for the treatment of retinal disease." (PMID 34831423, 2021). "The preferential expression of NGB in the retina suggests that it can be sensitive to multiple retinal diseases." (PMID 34831423, 2021). "Therefore, the exact correlation between NGB and retinal status is worth to be further deepened for defining NGB functionality in the retina and its possible role as a general biomarker of retinal disease." (PMID 34831423, 2021).
spinal cord injury (1 paper, 2013). Penetrating and non-penetrating injuries to the spinal cord resulting from traumatic external forces (e.g., WOUNDS, GUNSHOT; WHIPLASH INJURIES; etc.). "This study aims to investigate the potentially protective effect of neuroglobin (Ngb) gene-modified bone marrow mesenchymal stem cells (BMSCs) on traumatic spinal cord injury (SCI) in rabbits." (PMID 23658829, 2013).
cancer (22 papers, 2010 to 2024). A tumor composed of atypical neoplastic, often pleomorphic cells that invade other tissues. "Notwithstanding this, the possible association between high levels of NGB and human cancer progression is still unclear and strongly debated." (PMID 34440755, 2021). "Overall, these data define a role of NGB as compensatory protein in the cell machinery activated in response to stress and as general stress adaptation marker of cancer cells susceptible to oxidative stress, oxygen and, as demonstrated here for the first time, even to nutrient willingness." (PMID 29216269, 2017). "In these malignancies, 17β-estradiol (E2) via ERα increases the levels of neuroglobin (NGB), a compensatory protein that protects cancer cells from stress-induced apoptosis, including chemotherapeutic drug treatment." (PMID 36768470, 2023). "Neuroglobin is a unique globin identified as a critical player in cancer cell adaptation and resistance to detrimental oxidative stress conditions." (PMID 36346805, 2022). "Some recent studies reported that cancer cells can produce neuroglobin (NGB), a monomeric globin, in response to oxidative stress." (PMID 33673398, 2021). "Human NGB overexpression has been suggested to shield neurons from mitochondrial dysfunctions and neurodegenerative disorders and to play a protective role in cancer cells." (PMID 33924212, 2021). "The role of NGB accumulation as a protective shield of cancer cells to cope with their stressful environment has been demonstrated in 17β-estradiol (E2)-sensitive cancer cells." (PMID 33924212, 2021). "The NGB immunoreactivity is barely detectable in the normal tissue, whereas cancer samples show a strong positive NGB staining in the epithelial cells." (PMID 34440755, 2021). "Intriguingly, NGB silencing renders MCF-7 cancer cells more prone to the apoptosis induced by the chemotherapeutic agent Paclitaxel, even in the presence of E2." (PMID 33924212, 2021). "E2/ERα-induced NGB accumulation in cancer cells represents an anti-apoptotic pathway, which abrogates the cell death induced by a chemotherapeutic agent (paclitaxel, Pacl)." (PMID 31936631, 2020). "More recently, independent studies indicate that NGB protein level is differently modulated by oxidative stress and hypoxia in diverse extra nervous cancer cell lines and tissues." (PMID 29216269, 2017). "As a whole, these data indicate that ROS-inducing compounds increase NGB protein levels in MCF-7 cancer cells activating specific and diverse pathways." (PMID 27149623, 2016). "Recently, it has been demonstrated that NGB is an E2 compensatory protein, which up-regulation counteracts apoptosis induced by oxidative stress in several cancer cell lines." (PMID 27149623, 2016). "In cancer cell lines, ERα is overexpressed respect to ERβ and mediates NGB expression upon E2 treatment." (PMID 27313512, 2016). "In all the E2-responsive cancer cells tested, E2 induced a dose- and time-dependent increase in NGB levels with a maximum effect at 10 nM (24 h)." (PMID 25299774, 2014). "This high NGB level seems to be essential for the E2 anti-apoptotic effects against the H2O2 toxicity in ERα-expressing cancer cells." (PMID 25299774, 2014). "The main aim of this paper was to evaluate the possibility that NGB is upregulated by E2 also in cancer cells, where NGB upregulation would increase cell survival after oxidative stress, acting as a mediator of E2 pro-oncogenic effects." (PMID 25299774, 2014). "More experiments are needed to better clarify the signal pathways involved in the regulation of NGB levels in cancer cells." (PMID 25299774, 2014). "In a wider ranging study it was found that neuroglobin was often upregulated and this lead the author to conclude that neuroglobin represents “a part of the defense repertoire that allow cancer cells to survive in hypoxic conditions”." (PMID 24710547, 2012).